NLRP3 (NLR family pyrin domain containing 3)
Diseases named in the same sentence as NLRP3 in open-access papers (continued):
Sharing a sentence is not in itself a finding about the gene and the disease.
Candida infection (continued). "Therefore, it could be speculated that NLRP3 is critical for mediating the myeloid response in the adrenal gland during candidiasis." (PMID 36389688, 2022). "Neutrophil influx into the Nlrc4-/- tongue was drastically reduced compared to either wild-type (wt) or Nlrp3-/- mice, and NLRC4 activation was crucial for the trafficking of neutrophils to the site of active Candida infection." (PMID 33119702, 2020). "Collectively, these studies reveal the tissue specific roles of the NLRP3 and NLRC4 inflammasome in innate immune responses against mucosal Candida infection." (PMID 22174673, 2011). "Here we show that mucosal expression of NLRP3 and NLRC4 is induced by Candida infection, and up-regulation of these molecules is impaired in NLRP3 and NLRC4 deficient mice." (PMID 22174673, 2011). "Expression levels of CAMP were dramatically elevated in WT buccal tissue following Candida infection, and this induction was dependent on NLRC4, NLRP3 and ASC." (PMID 22174673, 2011). "Interesting patterns of induction of the IL-17 family by Candida infection were observed; IL-17A was dependent on NLRC4, NLRP3 and ASC whereas IL-17F was only dependent on NLRP3 with comparable induction seen in WT, NLRC4 and ASC deficient mice." (PMID 22174673, 2011). "IL-1β production is required for an effective host response to Candida infection, and mice lacking critical inflammasome components such as NLRP3, ASC, or caspase-1 are hypersusceptible to C. albicans-induced sepsis." (PMID 34795266, 2021). "Therefore, it could be speculated that NLRP3 and CR3 are critical for mediating the myeloid response in the adrenal gland during candidiasis." (PMID 36389688, 2022). "Interestingly, unlike most models of candidiasis where NLRP3 mediates protection, fungal burden in knockouts was not altered during infection, suggesting that, in the case of VVC, NLRP3 drives immunopathogenic inflammation." (PMID 32106438, 2020).
Chronic colitis (19 papers, 2017 to 2024). A chronic inflammatory disease of the large intestine (colon, cecum and rectum). "In contrast, NLRP3 inflammasome protects against the bowel inflammation associated-tumor formation in chronic stages but promotes colon cancer in the early stage of the chronic colitis-ulcerative colitis, Crohn’s disease." (PMID 38649928, 2024). "Chronic colitis is associated with elevated levels of Fusobacterium species, which may contribute to inflammation by invading intestinal cells, activating the NLRP3 inflammasome, and dysregulating the microbiome." (PMID 37513865, 2023). "With a discerning and inquisitive interest, we read the paper “BAFF Blockade Attenuates DSS-Induced Chronic Colitis via Inhibiting NLRP3 Inflammasome and NF-κB Activation” published in Frontiers in Immunology." (PMID 39776908, 2024). "The most salient finding of the study is that MCC950 decreased the severity of chronic colitis in Winnie mice by specific inhibition of NLRP3 inflammasome activation." (PMID 29872077, 2018). "Conversely, in chronic colitis, where a disruption of the intestinal epithelial barrier and an exacerbation of the mucosal immune response occur, the overactivation of NLRP3 inflammasome results to be harmful to the host." (PMID 28179906, 2017). "In the young male with high level of the NLRP3 inflammasome activity especially the IMIDs-chronic colitis patients, testosterone could modulate the NLRP3 inflammasome activity and promoting the NLRP3 inflammasome-related tumor genesis activity." (PMID 38649928, 2024). "Recent studies have suggested that dysregulation of the NLRP3 inflammasome in response to changes in the gut microbiota could contribute to the development of chronic colitis." (PMID 37513865, 2023). "Chronic colitis can be triggered by various factors that activate the NLRP3 inflammasome." (PMID 37513865, 2023). "Furthermore, we found that β-hydroxybutyrate may help mitigate gut inflammation in chronic colitis by inhibiting NFκB and NLRP3 inflammasome activation and restraining oxidative stress as revealed also by correlation analysis." (PMID 37513865, 2023). "In a spontaneous chronic colitis mouse model, MCC950 reduced the severity of chronic colitis through the inhibition of NLRP3 inflammasome activation." (PMID 39684769, 2024). "On one hand, NEK7 interacted with NLRP3 to regulate NLRP3 inflammasome activation, thereby modulating the pyroptosis in MODE-K cells and DSS-induced chronic colitis in mice." (PMID 38482005, 2024). "More relevantly, NEK7 interacted with NLRP3 to activate the NLRP3 inflammasome activation, thereby enhancing the pyroptosis in MODE-K cells and DSS-induced chronic colitis in mice." (PMID 38467948, 2024). "Our study found that in rats with chronic colitis, the mRNA expression of ASC and NLRP3 was significantly higher than in normal rats." (PMID 37513865, 2023). "NEK7 interacts with NLRP3 to modulate NLRP3 inflammasome activation, therefore modulating the pyroptosis in MODE-K cells and DSS-induced chronic colitis in mice." (PMID 31787755, 2019). "In conclusion, NEK7 interacts with NLRP3 to modulate NLRP3 inflammasome activation, therefore modulating the pyroptosis in MODE-K cells and DSS-induced chronic colitis in mice." (PMID 31787755, 2019). "Furthermore, our investigation revealed a negative correlation between the levels of β-hydroxybutyrate in rats with chronic colitis and several inflammatory markers, including MPO activity, ROS production, NLRP3 levels, caspase-1 activity, NFκB DNA binding activity, and the NGSDMD." (PMID 37513865, 2023).
Encephalopathy (19 papers, 2017 to 2025). Encephalopathy is a term that means brain disease, damage, or malfunction. "Previous studies have shown that puerarin protects against myocardial IRI injury, cell damage caused by retinal IRI, and encephalopathy caused by brain IRI by inhibiting NLRP3 inflammasome." (PMID 38055404, 2023). "In fact, SIRT1 activation by Resveratrol prevented NLRP3 expression and IL-1β cleavage in hippocampus of mice with sepsis-associated encephalopathy." (PMID 31327964, 2019). "Unconjugated bilirubin activates microglial NLRP3 inflammasomes, leading to neuronal damage and bilirubin-induced encephalopathy." (PMID 41149694, 2025).
glomerulosclerosis (19 papers, 2016 to 2025). A hardening of the kidney glomerulus caused by scarring of the blood vessels. "High activation of NLRP3 is associated with a reduced density of podocytes, glomerular sclerosis and volume increase in human glomeruli, and also triggers an inflammatory condition that thereby mediates kidney injury." (PMID 39732713, 2024). "Human kidney tissue showed significant associations of higher glomerular transcript expression of NLRP3 with higher global glomerulosclerosis, glomerular hypertrophy and reduced podocyte density which supports this further." (PMID 37487005, 2023). "Mice with NLRP3 knockout exhibit a noticeable attenuation in foot cell damage induced by elevated homocysteine and in the progression of glomerulosclerosis." (PMID 41357229, 2025). "first demonstrated in a hyperhomocysteinemia model that NLRP3 inflammasome activation in podocytes induces foot process effacement, contributing to glomerulosclerosis and proteinuria." (PMID 41357229, 2025). "Mice with podocyte-specific Sirt1 knockdown increase their inflammation-related markers and exacerbate NLRP3 inflammatory vesicle activation, leading to increased glomerulosclerosis and proteinuria." (PMID 38347622, 2024). "Higher transcript expression for NLRP3 in human glomeruli was accompanied by reduced podocyte density and increased global glomerulosclerosis and glomerular volume." (PMID 37487005, 2023). "In patients with DKD, the production of NLRP3 inflammasome correlates with glomerulosclerosis, interstitial fibrosis and tubular atrophy." (PMID 32992874, 2020). "Strong evidence has confirmed that NLRP3 inflammasome formation and activation are important molecular mechanisms triggering podocyte injury and ultimately resulting in glomerular sclerosis during hHcy." (PMID 32106480, 2020). "Recently, we have confirmed that the overproduction of ceramide by lysosomal ASM induces NLRP3 inflammasome activation in podocytes, leading to proteinuria and glomerulosclerosis." (PMID 32106480, 2020). "It was found that D-ribose induced NLRP3 inflammasome formation and activation, which led to podocyte injury and glomerular sclerosis in WT mice." (PMID 31737627, 2019). "We found that HFD treatment enhanced the Asm activity and ceramide production, which was attributed to NLRP3 inflammasome activation in glomeruli and ultimately led to glomerulosclerosis." (PMID 26980705, 2016). "Therefore, the inhibition of the NLRP3 inflammasome can ameliorate DN-related podocyte injury and glomerulosclerosis." (PMID 37638046, 2023). "Notably, activation of the NLRP3 inflammasome in podocytes promotes glomerular inflammation and glomerulosclerosis progression." (PMID 36387904, 2022). "In hyperhomocysteinemia, activation of the NLRP3 inflammasome has been shown to occur in the contexts of podocyte damage and glomerular sclerosis, and reductions of NADPH oxidase levels, knockdown of ASC, or inhibition of caspase-1 may have a protective effect." (PMID 34267672, 2021). "Accumulating evidence shows that the formation and activation of Nod-like receptor protein 3 (NLRP3) inflammasome in podocytes may instigate glomerular inflammation and lead to ultimate glomerular sclerosis in response to pathological stimuli such as hyperhomocysteinemia (hHcy), obesity and DM." (PMID 31737627, 2019). "Homocysteine-induced podocyte injury and glomerulosclerosis involve NOX activation and endogenously generated superoxide anion and H2O2 that mediate the NLR family pyrin domain containing 3 (NLRP3) inflammasome formation." (PMID 35327595, 2022). "On the contrary, inhibition of NLRP3 by MCC950 in diabetic animals exhibited adverse renal effects including enhanced inflammation, oxidative stress and glomerulosclerosis." (PMID 35048962, 2022).
glomerulosclerosis (continued). "The present study was designed to test the hypothesis that D-ribose induces NLRP3 inflammasome formation and activation in podocytes in an AGEs dependent manner, which will be an important triggering mechanism leading to podocyte injury and glomerular sclerosis." (PMID 31737627, 2019). "Sirt3 ameliorates pathological renal injuries such as inflammatory cell infiltration, glomerulosclerosis, and interstitial inflammation in IgAN mice by mediating autophagy to inhibit the activation of the NOD-like receptor pyrin domain containing 3 (NLRP3) inflammasome." (PMID 38347622, 2024). "In Asc gene knockout mice, D-ribose failed to produce NLRP3 inflammasome activation, which prevented D-ribose-induced podocyte injury and glomerular sclerosis." (PMID 31737627, 2019).
ovarian carcinoma (19 papers, 2019 to 2025). A malignant neoplasm originating from the surface ovarian epithelium. "The results indicated low miR-22 expression and NLRP3 overexpression in ovarian cancer tissues and cells, with miR-22 downregulation associated with poor prognosis." (PMID 40718836, 2025). "Overexpression of NLRP3 and other related proteins is a marker associated with the progression of ovarian cancer." (PMID 40718836, 2025). "Further, NLRP3 inflammasome activation has been linked to promoting pyroptosis, a form of programmed cell death, in cervical and ovarian cancer cells, affecting cancer cell viability and survival." (PMID 39769450, 2024). "Meanwhile, the expression level of NLRP3 was increasing from stage II to stage IV of ovarian cancer patients, suggesting that NLRP3 was positively linked to the deterioration of ovarian cancer." (PMID 37304662, 2023). "Only a few studies have been conducted that elucidate the relationship between NLRP3 and ovarian cancer prognosis, but they all point towards a higher level of NLRP3- and NLRP3-associated components being related to a worse prognosis." (PMID 35877745, 2022). "It has been shown that increased NLRP3 in ovarian cancer is associated with overall survival." (PMID 39769450, 2024). "Finally, immune infiltration analysis using TIMER2 found that NLRP3 expression levels were significantly positively linked to the proportions of T cells, neutrophils, macrophages, and myeloid dendritic cells in ovarian cancer tissues." (PMID 37304662, 2023). "Data from The Cancer Genome Atlas program comparing NLRP3 expression in pan-cancer and normal tissues showed higher expression in ovarian cancer, correlating with reduced overall survival." (PMID 40718836, 2025). "Another study on PFKFB3 in ovarian cancer found that PFKFB3 promotes ovarian cancer metastasis by suppressing the NLRP3 axis, reducing pyroptosis, and enhancing the Warburg effect." (PMID 40718836, 2025). "For example, one study reported NLRP3 overexpression in ovarian cancer cells, and bioinformatics analysis further explored the role of NLRP3 in promoting OvCa progression." (PMID 40718836, 2025). "This indirectly confirms the protective role of NLRP3-mediated pyroptosis in preventing ovarian cancer metastasis and progression." (PMID 40718836, 2025). "Of note, NLRP3 was reported to have an aberrantly high expression in ovarian cancer, and NLRP3 inflammasome participated in the development of ovarian cancer." (PMID 37304662, 2023). "Secondly, this study preliminarily explored the molecular mechanism of NLRP3 in DDP-resistant ovarian cancer, and the in-depth research focusing on its potential mechanism is deserved to be conducted in our future work." (PMID 37304662, 2023). "Next, a series of cellular biological activities were measured to assess the regulation of NLRP3 in DDP-resistant ovarian cancer." (PMID 37304662, 2023). "Carboplatin therapy increases the activation of the NLRP3 inflammasome in macrophages, indicating NLRP3 implications for ovarian cancer and potential chemoresistance." (PMID 37752941, 2023). "NLRP3 was overexpressed in ovarian cancer, correlated with poor survival, and upregulated in DDP-resistant ovarian cancer tumors and cells." (PMID 37304662, 2023). "Here, we aimed to assess the expression level of NLRP3 in ovarian cancer with DDP resistance, clarify its potential regulatory role, and offer new therapeutic strategies for the advancement of chemoresistance in ovarian cancer." (PMID 37304662, 2023). "NLRP3 knockdown hindered the malignant process of DDP-resistant ovarian cancer cells, providing a potential target for DPP-based ovarian cancer chemotherapy." (PMID 37304662, 2023). "The NLRP3 level in DDP-resistant ovarian cancer tumors and cell lines (SKOV3/DDP and A2780/DDP) was evaluated by applying immunohistochemical staining, western blot, and qRT-PCR." (PMID 37304662, 2023).
ovarian carcinoma (continued). "To understand the role of NLRP3 in DDP-resistant ovarian cancer, we first detected NLRP3 levels in patients with DPP resistance." (PMID 37304662, 2023). "NLRP3 is suggested to be a target for monitoring DDP resistance in ovarian cancer and improving therapeutic outcomes." (PMID 37304662, 2023). "Bioinformatics analysis was conducted to examine the role of Nod-like receptor protein 3 (NLRP3) in ovarian cancer." (PMID 37304662, 2023). "NLRP3 is involved in ovarian cancer chemoresistance with downregulation increasing drug sensitivity in gemcitabine‐resistant cell lines and overexpression inducing IL‐1β, EMT, and Wnt/β‐catenin signaling." (PMID 37752941, 2023). "Based on the indicated role of NLRP3 in malignant diseases, we analyzed the expression profile of NLRP3 in ovarian cancer depending on GEO and TCGA databases." (PMID 37304662, 2023). "Taken together, the current research highlights the specific role of NLRP3 in DDP-resistant ovarian cancer." (PMID 37304662, 2023). "Here, it is the first time to be verified that NLRP3 serves a vital role in DDP-based chemoresistance of ovarian cancer." (PMID 37304662, 2023). "There is a need for further research into the downregulation of NLRP3 and its effects on ovarian cancer." (PMID 35877745, 2022). "NLRP3 was up-regulated in ovarian cancer, and the expression of NLRP3 was negatively correlated with miR-22." (PMID 34299149, 2021). "Additionally, downregulation of NLRP3 enhances gemcitabine sensitivity in ovarian cancer (GRC) cells, potentially overcoming drug resistance and improving therapeutic efficacy." (PMID 40718836, 2025). "Polydatin inhibits NLRP3 inflammasome activation and prevents ovarian cancer progression." (PMID 39769450, 2024). "Citric acid prevents ovarian cancer cell growth via NLRP3-mediated pyroptosis." (PMID 39769450, 2024). "However, a few studies have highlighted NLRP3’s role in tumorigenesis and cancer progression in ovarian cancers." (PMID 39769450, 2024). "Similarly, citric acid has been shown to prevent ovarian cancer cell growth through caspase-4, thioredoxin-interacting protein, and NLRP3 inflammasome-mediated pyroptosis." (PMID 39769450, 2024). "However, a knowledge gap exists concerning the impacts of NLRP3 inflammasome on ovarian cancer with DPP resistance." (PMID 37304662, 2023). "The survival assay followed by Cox regression analysis revealed that patients with a higher level of NLRP3 had a poorer survival probability, and NLRP3 might act as an independent prognostic gene in ovarian cancer." (PMID 37304662, 2023). "The findings revealed that NLRP3 was overexpressed in response to DDP-resistant ovarian cancer." (PMID 37304662, 2023). "Greater NLRP3 expression was related to worse overall survival in ovarian cancer." (PMID 37752941, 2023). "Furthermore, NLRP3 signaling and persistent sterile inflammation may mark the early stages of ovarian cancer development." (PMID 40718836, 2025). "NLRP3 partially countered miR-22’s regulatory effects on cell proliferation and EMT in ovarian cancer cells." (PMID 40718836, 2025). "Silencing of NLRP3 can weaken drug resistance through repressing cell proliferation, invasion, and EMT in DDP-resistant ovarian cancer cells." (PMID 37304662, 2023). "Although inflammation has been shown to be a risk factor responsible for developing ovarian cancer, the role of NLRP3 inflammasome in ovarian cancer is not well studied when compared to other types of cancers." (PMID 39769450, 2024). "NLRP3 knockdown could effectively block cell proliferation, invasion, and EMT, while it promotes apoptosis in ovarian cancer cells with DDP resistance." (PMID 37304662, 2023). "Furthermore, we evaluated the NLRP3 level in ovarian cancer cell lines (A2780 and SKOV3) and their DDP-resistant forms and found that NLRP3 was upregulated in A2780/DDP and SKOV3/DDP cells." (PMID 37304662, 2023).
ovarian carcinoma (continued). "For instance, the early microenvironment of ovarian cancer may induce the production of DAMPs, which may subsequently activate AIM2 and NLRP3 inflammasomes." (PMID 37752941, 2023). "Collectively, the data revealed that NLRP3 knockdown and the inactivation of NLRP3 inflammasome might weaken the malignant phenotype of ovarian cancer with DDP resistance and regulate the chemoresistance of ovarian cancer cells to DDP-based therapy." (PMID 37304662, 2023).